AFP (alpha fetoprotein)
Diseases named in the same sentence as AFP in open-access papers (continued):
Sharing a sentence is not in itself a finding about the gene and the disease.
tumor (continued). "Compared to C2, the C1 subtype exhibited significantly higher serum alpha-fetoprotein (AFP) levels, poorer pathological grade, larger tumor size, and more advanced TNM stage." (PMID 41048998, 2025). "Tumor cells exhibited a yolk sac tumor profile that included strong reactivity with SALL-4 and focal/weak reactivity with AFP and glypican-3." (PMID 41510478, 2025). "This study showed that the tumor morphology (TBS), AFP levels, and the recipient MELD-Na were significantly associated with overall survival by the multivariable analysis." (PMID 40709064, 2025). "Of particular note, all five tumor markers CA125, CA19-9, CEA, HE4, and AFP were selected as significant predictors." (PMID 41300279, 2025). "The model included the four tumor markers (CEA, CA19-9, CA72-4, AFP), the inflammatory markers (CRP, ESR, fibrinogen), and the AJCC stage (treated as an ordinal variable from I to IV)." (PMID 40299527, 2025). "AFP levels are elevated in response to the biological behavior of HCC, contributing to tumor proliferation, invasion, and metastasis." (PMID 40857604, 2025). "PermSurvDNN consistently identified 12 key predictors including alpha-fetoprotein (AFP), liver fibrosis score, age, tumor size, grade, and others - each of which has been clinically validated in HCC prognosis." (PMID 41256539, 2025). "A prediction model for OS in the training cohort (OS-nomo, C-index=0.71), including alpha-fetoprotein (AFP), estimated hepatectomy extent, and tumor burden score (TBS) as independent factors (all P<0.05), was constructed." (PMID 40697370, 2025). "Tumor cells were identified using EPCAM, KRT18, and AFP as markers, while T/NK cells were identified by using the markers CD3D, CD3E, and GZMA." (PMID 40740783, 2025). "Based on this, we combined AFP with tumor shape irregularity to develop and validate the ATSI score for predicting survival and tumor response to immunotherapy." (PMID 39714631, 2025). "Univariate COX regression analysis was performed in the matching cohort, and AFP, ALT, AST, ALB, tumor diameter, PVTT and TACE were statistically significant." (PMID 41200181, 2025). "Alpha-fetoprotein (AFP), the most widely studied serum biomarker for HCC, correlates with viable tumor burden; however, only half of patients with HCC have elevated AFP prior to Tx, limiting its utility to assess HCC TR." (PMID 40307890, 2025). "Meanwhile, serum biomarkers (e.g., alpha-fetoprotein [AFP], des-gamma-carboxy prothrombin [DCP]) reflect tumor biological behavior and therapeutic response, functioning as key quantitative indicators for dynamic efficacy evaluation." (PMID 41267991, 2025). "Elevated tumor markers included PIVKA-II at 34,330 mAU/mL and alpha-fetoprotein (AFP) at 13.7 ng/mL." (PMID 41450371, 2025). "As for tumor markers, this study included CA125, CA199, CA724, HE4, AFP, CEA, ROMA premenopausal and postmenopausal indexes." (PMID 39911631, 2025). "Hence, compared with AFP or tumor size, ATR may be a more suitable prognostic marker." (PMID 40857604, 2025). "The integration of AFP and CRP into the CRAFITY score provides a mechanistically informed and clinically accessible framework that captures both tumor-intrinsic characteristics and systemic host immune status." (PMID 41358154, 2025). "Multivariate analyses identified AFP, ALB, tumor diameter, PVTT, TACE, and adjuvant therapy as independent predictors of OS, while AFP, multiple tumors, MVI, PVTT, TACE, and adjuvant therapy were associated with DFS." (PMID 41200181, 2025). "This study evaluated thrombocyte counts and clotting parameters (INR, Prothrombin Activity, aPTT) in relation to tumour markers (CEA, CA19-9, CA125, AFP) within different histopathological groups (adenocarcinoma, benign lesions, metaplasia)." (PMID 40332145, 2025).
tumor (continued). "The results show that when considering vascular invasion, sex, chemotherapy, AFP, PDW, lymph node invasion, HBsAg, tumor size, tumor number, tumor differentiation, and other previously common prognostic factors, HBV has significant prognostic value." (PMID 41128607, 2025). "For RFS, significant predictors included tumor number, tumor differentiation, preoperative SII, postoperative PIVKA-II, and postoperative alpha-fetoprotein (AFP) levels." (PMID 40808940, 2025). "TAAs are usually overexpressed in tumor cells, typically including carcinoembryonic antigen (CEA), prostate-specific antigen (PSA), alpha-fetoprotein (AFP), cancer antigen 125 (CA125), and mucin 1 (MUC1)." (PMID 39789208, 2025). "The very low false-positive rate of M371 documented in the present series unveils some minor analogies with the established serum tumour markers of GCT, human beta chorionic gonadotropin (bHCG) and alpha fetoprotein (AFP)." (PMID 39888414, 2025). "To further assess the prognostic value of dynamic changes in AFP and tumor size, we performed stratified RCS analyses according to baseline AFP levels and baseline tumor size." (PMID 40934000, 2025). "Age, AFP, IAT modality, and tumor burden were identified as independent predictors of OS in the multivariate analysis." (PMID 41199230, 2025). "Multiple tumor markers, including carbohydrate antigen 199, neuron-specific enolase, prostate-specific antigen (PSA), squamous cell carcinoma antigen, free PSA, alpha-fetoprotein (AFP), and carcinoembryonic antigen (CEA), were within normal limits." (PMID 39697257, 2025). "Tumor marker screens, namely, prostate-specific antigen (PSA), carcinoembryonic antigen (CEA), carbohydrate antigen 19-9 (CA 19-9), alpha-fetoprotein (AFP), and beta-human chorionic gonadotrophin (B-HCG), were however negative." (PMID 39897230, 2025). "Factors such as baseline AFP levels, liver stiffness, Child-Pugh class, NLR, and tumor size were significant predictors of treatment success." (PMID 40308490, 2025). "The study variables include age, sex, BMI, abdominal surgery history, ASA grade, ECOG score, tumour‐to‐anal margin distance, pathological diagnosis, cTNM stage, preoperative tumour markers (CEA, AFP, CA19‐9), and neoadjuvant chemotherapy." (PMID 39524013, 2025). "Although its diagnostic efficacy alone is limited, its combination with imaging and other biomarkers, such as AFP and DCP, can improve the accuracy of the assessment of tumor angiogenic activity and response to therapy." (PMID 40221793, 2025). "To address these limitations, we newly applied PSM to adjust for confounding factors such as age, gender, ECOG-PS, etiology, muscle atrophy, AFP, ALBI score, tumor size, number of treated lesions, and vascular invasion." (PMID 40940946, 2025). "Tumor markers, including CEA, CA 19-9, and/or AFP, were reported in nine cases and were normal in all but one, which reported a borderline CA 19-9." (PMID 40017578, 2025). "Tumor diameter was the biggest weighted parameter in the MoRAL-AI, followed by age, PIVKA-II, and AFP." (PMID 40218170, 2025). "Tumor marker testing yielded the following results: NSE 19.90 (0–16.3) ng/ml, CF21-1 4.52 (0–3.3 ng/mL), AFP 6.5 (0–7 ng/mL), CEA 3.73 (0–6.5 ng/mL), Ferritin 136.00 (30–400 ng/mL), carbohydrate antigen CA199 2.75 (0–27 U/mL), CA50 0.50 (0–25 IU/mL)." (PMID 40313546, 2025). "The Boruta algorithm selected 19 significant features, including tumor markers (CA125, HE4, CEA, CA19-9, AFP), hematological indices, liver function tests, and electrolytes." (PMID 41300279, 2025). "We performed a Cox regression analysis including the following variables: age, gender, ECOG performance status, etiology, muscle atrophy, AFP level, modified ALBI grade, tumor size, number of treated lesions, vascular invasion, and treatment modality." (PMID 40940946, 2025).
tumor (continued). "Univariate and multivariate Cox regression analyses demonstrated that the prognostic factors affecting OS were distant metastasis, maximum tumor diameter, TACE duration, and alpha-fetoprotein (AFP) level (p < 0.05)." (PMID 40678062, 2025). "In clinical practice, immunoenzymatic assays (ELISAs) are most commonly used to determine classic tumor markers such as CA-125, HE4, AFP, β-hCG and LDH." (PMID 41373846, 2025). "Laboratory data and tumor markers were as follows: AST: 54 U/L, ALT: 50 U/L, LDH: 185 U/L, ALP: 138 U/L, γ-GTP: 48 U/L, total bilirubin: 1.2 mg/dL, AFP: <0.9 ng/mL, PIVKA-II: 9795 mAU/mL, CEA: 4.2 ng/mL." (PMID 41440222, 2025). "AFP and CEA are the most commonly used protein tumor markers and are briefly described in the following text." (PMID 40723883, 2025). "Their criteria were: total tumor diameter (TTD) ≤8 cm; or TTD >8 cm, well and moderate differentiation, and preoperative AFP level ≤100 ng/ml." (PMID 40709064, 2025). "Serum concentrations of AFP and CEA were markedly elevated in mice bearing EST compared with all control groups, indicating a higher tumor burden." (PMID 41228521, 2025). "The tumor markers alpha-fetoprotein (AFP), human chorionic gonadotropin (HCG), and lactate dehydrogenase (LDH) are widely recognized as tumor markers, and their levels have been correlated with cancer prognosis." (PMID 40526183, 2025). "Meanwhile, subgroup analysis showed that abnormal PKM expression correlated with age, tumor size, tumor differentiation, vascular invasion, tumor embolus, ALT, AFP, and clinical stage." (PMID 41206438, 2025). "In vivo, an orthotopic xenograft mouse model demonstrated effective tumor targeting and volume quantification by immuno-PET, correlating strongly with serum AFP." (PMID 40722645, 2025). "Other tumor markers, including squamous cell carcinoma antigen (SCC), alpha-fetoprotein (AFP), carbohydrate antigen 15-3 (CA15-3), and carbohydrate antigen 19-9 (CA19-9), remained within normal ranges." (PMID 41293259, 2025). "ROC analyses of nine tumor markers (CEA, CA19–9, CYFRA, SCCA, AFP, PSA, CA125, CA15–3, and NCC-ST439) showed inadequate performance when used individually." (PMID 41282421, 2025). "The benefits of this approach are evident even in patients with poor liver function, elevated alpha-fetoprotein (AFP) levels, and advanced tumor stages." (PMID 41157241, 2025). "The AUCs for serological inflammation biomarkers ranged from 0.53 to 0.60 for PLR, NLR, and SII, while the AUCs for tumor biomarkers ranged from 0.52 to 0.64 for CEA, CA72‐4, CA125, CA19‐9, and AFP." (PMID 41187909, 2025). "The results showed that HBV+ patients had a tumor size ≥5 cm, HBsAg was positive, CA125, GGT, and alpha-fetoprotein (AFP) were normal, and ALT, AST, Hb, platelet distribution width (PDW), PT, and INR were abnormal (P < 0.05)." (PMID 41128607, 2025). "Other clinical characteristics and pathologic factors that may influence prognosis, including race, body mass index, viral cause, AFP, extrahepatic disease, and tumor grade, were also indistinguishable between complete responders and other patients in both the IMbrave150 and multicenter cohorts." (PMID 39998829, 2025). "In this study, the tumour markers analyzed included carcinoembryonic antigen (CEA), a-enolase (ENO1), a-fetoprotein (AFP), and calprotectin (CP) to detect digestive system cancer." (PMID 40821642, 2025). "The median MELD score was 10 (IQR: 8-14), median AFP level was 8 ng/mL (IQR: 4-25), largest tumor size was 2 cm (IQR: 1.1-3.0), and median tumor count was 1 (IQR: 1-2)." (PMID 40629061, 2025). "The AUCs of AFP, BCLC, and tumor size alone were 0.683 (95% CI: 0.511–0.854, p = 0.052), 0.772 (95% CI: 0.619–0.926, p = 0.004), and 0.754 (95% CI: 0.600–0.909, p = 0.006), respectively." (PMID 40075616, 2025). "Tumor marker levels, including carcinoembryonic antigen (CEA) and alpha-fetoprotein (AFP), were within normal ranges." (PMID 41357569, 2025).
tumor (continued). "Our study proposes the CRAFITY-100 RULE, which integrates baseline inflammatory and tumor markers (CRP, AFP, PIVKA-II) with their early kinetic changes, to better stratify patients with unresectable HCC undergoing immunotherapy." (PMID 41008900, 2025). "The nomogram was developed based on the following eight factors: BCLC, treatment, tumor diameter, up to 7 criteria, presence of PVTT, ascites, times of interventional treatments, and AFP." (PMID 40376592, 2025). "The patient responded favorably to treatment with icaritin and thalidomide, which resulted in a reduction in alpha‐fetoprotein (AFP) levels and tumor size." (PMID 40035422, 2025). "Furthermore, the combination of mSEPT9 and other biomarkers (such as AFP) has been emphasized in recent research, not only to increase sensitivity for malignant tumor diagnosis but also to predict overall survival, microvascular invasion, and tumor proliferation." (PMID 40017695, 2025). "Toso and colleagues investigated 6,478 patients who underwent LT and published their extended criteria as “total tumor volume and AFP” (TTV-AFP) criteria proposed the following rules: tumor volume <115 cm3 and AFP levels under 400 ng/ml in 2015." (PMID 40709064, 2025). "Distant metastasis, maximum tumor diameter, TACE frequency, and AFP levels are important prognostic factors that affect OS in patients." (PMID 40678062, 2025). "The elevated level of AFP in patients with HCC is generally related to more aggressive tumor biology and a higher tumor burden, indicating poor treatment efficacy." (PMID 41458596, 2025). "The AUC values ranged from 0.739 (95% CI: 0.569–0.910, p = 0.012) for AFP and BCLC to 0.780 (95% CI: 0.629–0.932, p = 0.003) for tumor size and BCLC." (PMID 40075616, 2025). "In case of acceptable tumor burden (tumors within Milan, UCSF, or up-to-seven), biological assessment via AFP-score, MoRAL score, or Metroticket 2.0 should be applied." (PMID 41375030, 2025). "Imaging—particularly MRI and high-resolution ultrasound—combined with serum tumor markers (LDH, hCG, AFP) and, when appropriate, immunohistochemical evaluation of OCT3/4 in gonadal biopsies, can help identify early neoplastic changes." (PMID 41303802, 2025). "All tumor markers, such as CEA (Carcinoembryonic Antigen), CA 19-9 (Carbohydrate Antigen 19-9), and AFP (Alpha-Fetoprotein), were within normal limits." (PMID 40517680, 2025). "Laboratory tests showed markedly elevated AFP (20,233 ng/mL), β-HCG (658.64 mIU/mL), NSE (20.4 ng/mL), and HE4 (72.6 pmol/L), while other tumor markers remained within normal limits." (PMID 41018086, 2025). "Serum AFP has long been monitored as a biomarker for HCC, reflecting active tumor growth or residual tumor cells." (PMID 40246743, 2025). "During the follow-up period, we also monitored the status of relevant tumor markers, including CEA, CA12-5, CA19-9, CA15-3, and AFP." (PMID 41170382, 2025). "Serum CST4 levels were quantified by ELISA alongside six conventional tumor markers (CEA, CA125, CA153, CA199, AFP, CA724)." (PMID 41040534, 2025). "The nebulized NLU showed better anti-tumor, anti-inflammatory, and anti-oxidative effects than oral nintedanib in terms of LDH, CEA, AFP, MDA, TNF-α, and IL-1β." (PMID 41625777, 2025). "Both tumor markers—specifically carcinoembryonic antigen (CEA), alpha-fetoprotein (AFP), and carbohydrate antigen 19-9 (CA19-9)—and systemic inflammatory indices were within normal reference ranges." (PMID 40735311, 2025). "In tumour-informed HCC cohorts, the median lead-time vs. AFP was ~8 months, supporting the use of treatment-triggering or imaging-escalation algorithms when ctDNA is positive." (PMID 41301037, 2025). "Tumor markers such as CA125, human epididymis protein 4, CA153, CA199, CEA, and AFP were all normal." (PMID 40901169, 2025).
tumor (continued). "In instances of discordance between morphology and biology—such as within-Milan tumours with high PET avidity and rising AFP/DCP—priority should be given to biology (e.g., intensified bridging or longer observation)." (PMID 41301037, 2025). "The RFS nomogram was constructed based on five key predictive factors: tumor number, tumor differentiation, preoperative SII, postoperative PIVKA-II level, and postoperative AFP level." (PMID 40808940, 2025). "With high baseline AFP and DCP levels, our patient achieved a complete response, although he presented tumor marker pseudoprogression during the three weeks after the first dose of tislelizumab." (PMID 40534866, 2025). "Clinicians are instructed to measure tumor markers, including serum hCG, LDH, AFP pre- and postoperatively." (PMID 39726664, 2025). "For OS, univariate analyses identified several variables as potential predictors, including age, PS, mALBI grade 2b or 3, multiple nodules, tumor diameter ≥4 cm, presence of MVI, serum AFP ≥100 ng/mL, serum DCP ≥100 mAU/mL, and treatment modality (CIRT)." (PMID 40879478, 2025). "Elevated expression of Type 1 T helper cells is known to increase tumor cells’ sensitivity to various treatments, and when combined with clinical parameters like TNM staging and AFP levels, it presents excellent predictability of early HCC recurrence." (PMID 40255404, 2025). "COLEC10 expression significantly correlated with tumor location, TNM staging, serum alpha-fetoprotein (AFP) levels, and survival rates." (PMID 40026364, 2025). "Alpha-fetoprotein (AFP) vaccines activated HCC immunity, with hAFP-DCs enhancing anti-tumor effects in mice." (PMID 40242773, 2025). "Overall, as already mentioned, serum levels of the tumor markers (S) have low sensitivity in identifying TGCT, AFP, and/or hCG serum levels are elevated in 73% of NSTs, while AFP is never elevated, and hCG is elevated in approximately 30% of SE cases." (PMID 40723290, 2025). "Accumulating data continue to suggest AFP, AFP-L3, DCP profiling provides a patient-specific and tumor-direct measure of biological aggressiveness with prognostic implications for short-term risk of progression to advance-stage disease." (PMID 41137977, 2025). "This group demonstrated significantly elevated levels of tumour markers such as CA 19-9, CEA, AFP, and CA-125 compared to other patients." (PMID 40332145, 2025). "Serum B-type natriuretic peptide was 160 pg/mL and pro-gastrin-releasing peptide (Pro-GRP) 426 pg/mL; other tumor markers (NSE, CEA, SCC, C21-1, and alpha-fetoprotein [AFP]) were normal." (PMID 40958226, 2025). "The lower positive rates of AFP, GPC3, GS, and CD34 in the TRG1a group further indicate a lower residual tumor burden and a more favorable tumor biology responded to conversion therapy." (PMID 41246344, 2025). "Except AFP/β-HCG/SCC, the abnormal rate of the other tumor markers were significantly different between these AID." (PMID 40660406, 2025). "Tumour markers such as CEA, CA 19-9, AFP, and CA-125 play a crucial role in the early detection and prognostic evaluation of gallbladder lesions." (PMID 40332145, 2025). "Integrating biomarkers such as AFP, DCP, radiomics, and circulating tumour DNA refines transplant eligibility and post-transplant surveillance." (PMID 41301037, 2025). "Serum tumor markers including carcinoembryonic antigen (CEA) and Alpha-fetoprotein (AFP) were within normal limits, and routine blood tests, biochemical profiles, and cranial MRI showed no significant abnormalities." (PMID 41229505, 2025). "Epithelial CSCs express EpCAM as a cell surface marker, and are characterized by high serum alpha-fetoprotein (AFP) levels, venous invasion, tumor proliferation, enhanced invasiveness, and high resistance to anticancer drugs." (PMID 40253402, 2025). "HCG, as well as AFP and LDH represent clinically used serum tumor markers of TGCT for primary diagnosis, staging, monitoring of therapeutic response, and follow-up." (PMID 40723290, 2025).